MIR6806 (microRNA 6806)
Synonyms: hsa-mir-6806
Gene: MicroRNA gene on chromosome 19 (58,334,688 to 58,334,751, forward strand). Ensembl gene ENSG00000277588.
Homologues: Orthologues: chimpanzee MIR6806 (100% identical).